PHLDA2 (pleckstrin homology like domain family A member 2)
Description:
Plays a role in regulating placenta growth. May act via its PH domain that competes with other PH domain-containing proteins, thereby preventing their binding to membrane lipids (By similarity).
Synonyms: BWR1C; HLDA2; IPL; TSSC3; BRW1C
Tractability: Antibody: UniProt places it where antibodies can reach, with medium confidence. PROTAC: ubiquitination databases record sites on it.
Gene: Protein-coding gene on chromosome 11 (2,928,273 to 2,929,420, reverse strand). Ensembl gene ENSG00000181649.
Subcellular location: Cytoplasm; Membrane
Subcellular location (Human Protein Atlas): Nucleoli
Gene Ontology:
Molecular function: protein binding; phosphatidylinositol phosphate binding
Biological process: apoptotic process; placenta development; positive regulation of apoptotic process
Cellular component: cytoplasm; membrane
Genetic constraint (gnomAD): Loss-of-function variants: 5 observed, 5.85 expected, observed/expected ratio (o/e) 0.85, 90% interval 0.44 to 1.68. That is too few expected variants to judge how well the gene tolerates losing a copy. Missense variants: 216 observed, 218.21 expected, observed/expected ratio (o/e) 0.99, 90% interval 0.88 to 1.11. Synonymous variants: 111 observed, 102.02 expected, observed/expected ratio (o/e) 1.09, 90% interval 0.93 to 1.27.
Homologues: Orthologues: macaque PHLDA2 (95% identical), dog PHLDA2 (76% identical), pig PHLDA2 (75% identical), guinea pig PHLDA2 (72% identical), rat Phlda2 (58% identical), mouse Phlda2 (57% identical), tropical clawed frog phlda2 (49% identical), zebrafish phlda2 (45% identical). Paralogues in human: PHLDA1 (40% identical), PHLDA3 (39% identical).
Diseases named in the same sentence as PHLDA2 in open-access papers:
PHLDA2 is named in the same sentence as 53 diseases in open-access papers, as found by Europe PMC text mining. Sharing a sentence is not in itself a finding about the gene and the disease. The quoted sentences say what the papers report.
osteosarcoma (17 papers, 2013 to 2024). A usually aggressive malignant bone-forming mesenchymal neoplasm, predominantly affecting adolescents and young adults. "In summary, our results reveal that upregulation of miR-214 is a frequent event and negatively associated with PHLDA2 expression in osteosarcoma." (PMID 31058093, 2019). "Our analysis revealed that miR-214 was a negative regulator of PHLDA2, which is overexpressed in osteosarcoma tissues and negatively associated with lung metastasis." (PMID 31058093, 2019). "However, only a few studies have reported on the relationship between PHLDA2 and human cancers, including the loss of PHLDA2 expression in complete hydatidiform moles, Wilms’ tumors, brain cancer and osteosarcoma." (PMID 29861842, 2018). "PHLDA2 inhibits tumorigenesis and metastasis in osteosarcoma patients via the PI3K/AKT/mTOR pathway." (PMID 32385195, 2020). "We also confirmed that miR-214 expression is required for maintaining radioresistance to apoptosis in osteosarcoma, which is mediated by the repression of PHLDA2 and activation of Akt pathway." (PMID 31058093, 2019). "Pleckstrin homology-like domain family A member 2 (PHLDA2) displays low expression in human osteosarcoma as a proapoptosis factor." (PMID 31058093, 2019). "For this purpose, a panel of miRNAs that contained potential binding sites of PHLDA2 were detected, and we show that miR-214 is the only miRNA that decreased PHLDA2 expression in osteosarcoma." (PMID 31058093, 2019). "Many studies have shown that PHLDA2 expression is decreased in osteosarcoma tissue and cell lines when compared with controls and that high levels of PHLDA2 is a predictor of good prognosis." (PMID 31105744, 2019). "The involvement of RanBP9 in regulating the PHLDA2 expression has been described previously; however, the transcriptional mechanism by which PHLDA2 is repressed in osteosarcoma has been elusive." (PMID 31058093, 2019). "We next investigated the molecular mechanism by which miR-214-triggered PHLDA2 downregulation led to radiation resistance in osteosarcoma cells." (PMID 31058093, 2019). "In summary, our results reveal that the upregulation of miR-214 as a frequent event in osteosarcoma contributes to radioresistance by regulating the PHLDA2/Akt pathway." (PMID 31058093, 2019). "PTHLH is associated with malignancy-related hypercalcemia, lactation, the expression of PHLDA2 is upregulated in osteosarcoma progression." (PMID 24068962, 2013). "In osteosarcoma, one type of aggressive bone tumor, PHLDA2 displayed decreased expression level, suggested a favorable prognosis for patients, and overexpressed PHLDA2 could impair tumorigenesis and metastasis both in vitro and in vivo." (PMID 39033192, 2024). "In addition, PHLDA2 has been observed to display abnormal expression patterns in several malignant tumors, such as glioma, hydatidiform mole, osteosarcoma, and colorectal cancer." (PMID 38827322, 2024). "PHLDA2 (TSSC3) has been reported to promote autophagy in osteosarcoma cells." (PMID 32385195, 2020). "The downregulation of PHLDA2 has been identified in several human cancers, including osteosarcoma." (PMID 31058093, 2019). "Additionally, upregulation of PHLDA2 induces osteosarcoma cell apoptosis, inhibited cell growth and tumorigenesis in vitro and in vivo." (PMID 31105744, 2019). "The miR-214/PHLDA2/Akt axis provides a new avenue toward understanding the mechanism of radiosensitivity and may be a potential target for osteosarcoma intervention." (PMID 31058093, 2019). "However, the precise mechanism by which PHLDA2 is suppressed remains poorly understood in osteosarcoma." (PMID 31058093, 2019). "However, the specific miRNAs that mediate the PHLDA2 inhibition needs to be explored to further see how they affect radiotherapeutic response of osteosarcoma." (PMID 31058093, 2019). "In addition, PHLDA2 has been reported to activate autophagy in osteosarcoma cells, which suggests that PHLDA2 may regulate autophagy in CRC cells." (PMID 32385195, 2020).
osteosarcoma (continued). "In addition, PHLDA2 downregulation facilitates EMT via the GSK-3β pathway in osteosarcoma cells." (PMID 32385195, 2020). "In addition, we further elucidate that miR-214 reduced apoptosis and promoted radioresistance in osteosarcoma via the PHLDA2 inhibition and Akt activation, which is partially antagonized by the expression of PHLDA2 cDNA lacking 3-UTR or PI3K inhibitor treatment." (PMID 31058093, 2019). "Finally, these findings strengthen a paradigm that miR-214 participates in the radioresistance of osteosarcoma by regulating the PHLDA2/Akt pathway and propose that PHLDA2/Akt could be a novel radiotherapeutic targets in osteosarcoma." (PMID 31058093, 2019). "Additionally, PHLDA2 has been shown to impact EMT and metastasis in osteosarcoma through the SRC/PI3K/AKT/mTOR and WNT/GSK3-β/β-catenin signaling pathway." (PMID 38827322, 2024).
colorectal cancer (9 papers, 2016 to 2024). A primary or metastatic malignant neoplasm that affects the colon or rectum. "PHLDA2 is an imprinted gene associated with several malignancies and can promote colorectal cancer proliferation and metastasis." (PMID 37414748, 2023). "Knockdown of PHLDA2 activated apoptosis and autophagy, eventually causing inhibition of tumor growth through AKT/mTOR signaling in both colorectal cancer and glioma." (PMID 39033192, 2024). "In this study, we observed for the first time that the expression level of PHLDA2 was up-regulated, consistent with the majority of cancers, including liver cancer, colorectal cancer, glioma, lung cancer." (PMID 39033192, 2024). "Based on previous research, it has been demonstrated that PHLDA2 plays a role in regulating EMT in colorectal cancer via the PI3K-AKT signaling pathway." (PMID 38827322, 2024). "PHLDA2 is a maternally imprinted gene associated with tumour progression and EMT in several malignancies, such as colorectal cancer and pancreatic ductal adenocarcinoma." (PMID 37414748, 2023). "Imprinted gene pleckstrin homology-like domain family A member 2 (PHLDA2) is upregulated in colorectal cancer, and its knockout stimulates autophagy via the PI3K/AKT pathway, reducing cell proliferation, invasion, migration, and EMT process." (PMID 33194736, 2020). "Correlations between PHLDA2 expression and clinicopathologic features in 99 colorectal cancer patients." (PMID 32385195, 2020). "For PHLDA2, up-regulation of PHLDA2 could lead to proliferation of tumor cells in liver cancer, glioma, and colorectal cancer." (PMID 39033192, 2024). "In contrast, our analysis showed that PHLDA2 is overexpressed in lung and colorectal cancers, and it may also be downregulated in pancreatic carcinoma." (PMID 38921000, 2024). "The expression of PHLDA2 was found to be elevated in colorectal cancer." (PMID 38921000, 2024). "Finally, high expression of SH2D3A has been reported to enhance the progression of ovarian cancer, and downregulation of PHLDA2 has been reported to significantly inhibit the development of colorectal cancer through the PI3K/AKT signaling pathway." (PMID 35712127, 2022). "In the present study, we demonstrated that the mRNA expression of SLC22A18 and PHLDA2, which are regulated by KCNQ1OT1 lncRNA spreading, was increased by the knockdown of β-catenin in colorectal cancer cells." (PMID 26868975, 2016).
fetal growth restriction (9 papers, 2011 to 2024). A fetus that does not grow beyond the 10th percentile of conventionally accepted weight for gestational age. "Previous studies demonstrated that elevated expression of PHLDA2 has been reported to be associated with fetal growth restriction." (PMID 39033192, 2024). "Abnormally increased placental PHLDA2 expression is associated with fetal growth restriction in human pregnancies and/or low birth weight." (PMID 28251419, 2017). "In contrast, biallelic expression of Phlda2, due to loss of imprinting, contributes to placental growth retardation and results in conceptuses with intrauterine growth restriction (IUGR)." (PMID 21854573, 2011). "In addition, elevated Phlda2 was found to drive fetal growth restriction (FGR) of transgenic offspring and impaired maternal care by their wildtype mothers." (PMID 34100083, 2021). "It has previously been suggested that PHLDA2 expression in the placenta could be used to postnatally identify types of fetal growth restriction and thus inform subsequent infant care." (PMID 26944942, 2016). "Pleckstrin homology-like domain family A member 2 (PHLDA2) was first highlighted as a potential fetal growth restriction gene in a 2006 study that reported elevated expression in the placenta of 9 out of the 38 fetal growth restriction (FGR) placentae." (PMID 25085993, 2014). "The results suggest that placental PHLDA2 may provide a biomarker for suboptimal skeletal growth in pregnancies uncomplicated by overt fetal growth restriction." (PMID 22100507, 2012). "Elevated expression of the imprinted gene PHLDA2 has been reported in a number of studies on LBW and fetal growth restriction, but correlation does not always equal causation." (PMID 25085993, 2014).
breast carcinoma (6 papers, 2018 to 2024). "We discovered and validated that peripheral blood DNA methylation of KCNQ1, KCNQ1OT1, and PHLDA2 at chromosome 11p15.4-15.5 is associated with breast cancer susceptibility." (PMID 35681632, 2022). "The migration and proliferation of breast cancer cells were significantly reduced when the PHLDA2 gene was silenced." (PMID 38921000, 2024). "The other study claims that the relationship between PHLDA2 expression and breast cancer patient survival is ambiguous and inconsistent." (PMID 38921000, 2024). "PHLDA2 knockdown restrains invasion and proliferation of breast cancer and inhibits the invasion and migration of pancreatic ductal adenocarcinoma, although the specific mechanisms of action are unclear." (PMID 32385195, 2020). "PHLDA1, a gene homologous to PHLDA2, inhibits autophagy in neuroblastoma and promotes autophagy in breast cancer cells." (PMID 32385195, 2020). "PHLDA1, a homologous gene of TSSC3 (PHLDA2) has been reported to regulate autophagy in breast cancer and neuroblastoma cells, which also suggested that TSSC3 might have the ability to regulate autophagy." (PMID 30092789, 2018).
lung carcinoma (5 papers, 2017 to 2024). "PHLDA2 expression is found to be induced by oncogenic EGFR/AKT signaling in lung cancers via the correlation of PHLDA2 expression with both p-AKT and EGFR mutations." (PMID 38921000, 2024). "Since we found that PHLDA2 expression correlates positively with AKT activation in lung cancer we then analyzed the effect of PHLDA2 on AKT activity by modulating PHLDA2 expression in lung cancer cells via overexpression and knockdown studies." (PMID 29861842, 2018). "Next, we demonstrated that in human lung cancer cell lines and primary lung cancer specimens PHLDA2 expression correlates with p-AKT suggestive of a direct regulation." (PMID 29861842, 2018). "Interestingly, we found PHLDA2 expression in 3 lung cancer cell lines with high p-AKT expression and 100% of cell lines without p-AKT expression also lacked expression of PHLDA2." (PMID 29861842, 2018). "Since we found that PHLDA2 inhibits AKT activation through interfering with AKT translocation to the plasma membrane and further showed that this is mediated by direct competition with AKT to bind membrane lipids, we next examined whether PHLDA2 acts as a functional tumor suppressor in lung cancer." (PMID 29861842, 2018). "In an immunohistochemical study, we find that PHLDA2 protein expression correlates positively with AKT activation in human lung cancers corroborating our data that PHLDA2 is induced upon oncogenic activation and might serve as a biomarker for AKT pathway activation." (PMID 29861842, 2018). "Since PHLDA2 is a downstream target of EGFR/ErbB2, we analyzed PHLDA2, p-Erk and p-AKT expression in multiple lung cancer cell lines and a tissue microarray prepared with 117 well annotated primary lung cancer samples." (PMID 29861842, 2018). "As 3 lung cancer cell lines with detectable p-AKT expression on the other hand had no PHLDA2 expression, expression in some cases appears to be regulated by a combination of factors other than p-AKT activation as well." (PMID 29861842, 2018). "PHLDA3 was previously shown to function as a unique AKT inhibitor through the depletion of membrane-bound phosphatidyl inositols, however, the physiological function of PHLDA2 in lung cancer has not been defined." (PMID 29861842, 2018). "We observed PHLDA2 expression in 3 lung cancer cell lines with high p-AKT expression and 100% of cell lines lacking p-AKT expression had absent expression of PHLDA2 as well suggestive of a correlation." (PMID 29861842, 2018). "In summary, our studies demonstrate that PHLDA2 is strongly regulated by EGFR/ErbB2 signaling and inhibits cell proliferation via repressing AKT activation in lung cancers in a negative feedback loop." (PMID 29861842, 2018).
brain cancer (3 papers, 2005 to 2024). A primary or metastatic malignant neoplasm affecting the brain. "During this multiomics analysis, we found that among the PHLDA family, PHLDA1 may be a therapeutic target for several cancers, including kidney, colon, and brain cancer, while PHLDA2 can be a therapeutic target for cancers of the colon, esophagus, and pancreas." (PMID 38921000, 2024). "Of particular interest are: FGF9 which may stimulate the growth of prostate cancer, brain cancer and endometrium; and IER3 (IEX-1), PHLDA2 (TSS3), IAPP (amylin), and SST, all of which may play roles in apoptosis." (PMID 15691381, 2005).
glioma (3 papers, 2020 to 2024). A benign or malignant brain and spinal cord tumor that arises from glial cells (astrocytes, oligodendrocytes, ependymal cells). "Interestingly, genes involved in gliomas development (IGF2, H19, PHLDA2/TSSC3, TRIM3, SLC22A18) are located in the gene locus 11p15.5 of the beta hemoglobin chain." (PMID 32183175, 2020).
liver cancer (3 papers, 2024 to 2025). An epithelial or non-epithelial malignant neoplasm that arises from the liver. "For instance, in hepatocellular carcinoma (HCC), HSPA8 functions as a co‐activator of the transcription factor ETV4, leading to the upregulation of PHLDA2, thereby facilitating the progression of liver cancer." (PMID 40099939, 2025). "Reportedly, via regulating the PI3K/AKT pathway, PHLDA2 affects EMT and autophagy, and inhibits the growth of colon cancer, and SOCS5 regulates autophagy pathway and promotes the transfer of liver cancer cells." (PMID 39428922, 2024).
lung adenocarcinoma (3 papers, 2017 to 2019). A carcinoma that arises from the lung and is characterized by the presence of malignant glandular epithelial cells. "Although the role of PHLDA2 in cancer is unclear, our data showed that PHLDA2 may potentially exert oncogenic effects in lung adenocarcinoma." (PMID 29285217, 2017). "However, PHLDA2 was also found to play oncogenic roles in lung adenocarcinoma." (PMID 31105744, 2019). "In the GSE10072 array, expression levels of CDKN2A, PHLDA2, and SFN are significantly upregulated in lung adenocarcinoma compared to normal lung tissue in several datasets, and NDRG4 is downregulated." (PMID 29285217, 2017). "The analysis of the effects from each gene expression on survival outcome indicated that 6 genes (AGR2, SPDEF, CDKN2A, CLDN3, SFN, and PHLDA2) play oncogenic roles, and 7 genes (PDK4, FMO2, CPED1, GNG11, IL33, BTNL9, and FABP4) act as tumor suppressors in lung adenocarcinoma." (PMID 29285217, 2017).
pancreatic ductal adenocarcinoma (3 papers, 2019 to 2023). An infiltrating adenocarcinoma that arises from the epithelial cells of the pancreas. "Furthermore, PHLDA2 promotes tumor formation in triple-negative breast cancer and in pancreatic ductal adenocarcinoma." (PMID 32385195, 2020). "In addition, high expression of PHLDA2 has also been observed in triple-negative breast cancer cell lines and pancreatic ductal adenocarcinoma, and represents poor prognosis." (PMID 31105744, 2019).
colon cancer (2 papers, 2024). "In contrast, low PHLDA2 expression was associated with poor clinical outcomes in patients with breast and colon cancer." (PMID 38921000, 2024).
hepatocellular carcinoma (2 papers, 2024 to 2025). A malignant tumor that arises from hepatocytes. "The findings above indicate a significant upregulation of PHLDA2 in hepatocellular carcinoma (HCC), which is associated with a poorer prognosis." (PMID 38827322, 2024). "Then, we searched PHLDA2 expression specifically in hepatocellular carcinoma (HCC) using the HCCDB database." (PMID 38827322, 2024). "PHLDA2 may exert regulatory control over the AKT signaling pathway, thereby facilitating the advancement of hepatocellular carcinoma (HCC)." (PMID 38827322, 2024).
lymph node metastasis (2 papers, 2024 to 2025). "The other gene PHLDA2, which has been reported to be associated with lymph node metastasis and TNM staging, had a higher expression level in epithelial cells of L‐CRC compared to R‐CRC." (PMID 39294858, 2024).